CCN1 (cellular communication network factor 1)
Diseases named in the same sentence as CCN1 in open-access papers (continued):
Sharing a sentence is not in itself a finding about the gene and the disease.
tumor (continued). "High expression of FOSB+, NEAT1+, or XIST+ tumor cell-associated genes such as FSTL3, VTN, PAPPA, CCN1, RRAD, and GPRIN3 may predict poor survival in patients with LUSC, suggesting that these genes act as prognosis biomarkers." (PMID 37430270, 2023). "CCN1 overexpression weakened the anti-tumour effects of VB and VB + LY294002." (PMID 35785168, 2022). "We speculated that VB may exert an anti-tumour effect by affecting the CCN1-mediated AKT/NF-κB signalling pathway in OC." (PMID 35785168, 2022). "CCN2 and CCN4 were highly expressed in tumor, and CCN1, 3, 5 were increased in the normal sample." (PMID 36589241, 2022). "This suggests that VB exerts an anti-tumour effect in OC in vivo by downregulating CCN1." (PMID 35785168, 2022). "For instance, CCN1 as a pro-inflammatory factor may promote tumor metastasis and progression in epithelial OC." (PMID 35785168, 2022). "Our further experiments exhibited that CCN1 overexpression weakened the anti-tumour effect of VB." (PMID 35785168, 2022). "The role of extracellular CCN1 to alter both the de-differentiation of muscle and stimulation of tumor aggressive phenotypes may be related to its ability to directly interact with the laminin-binding integrin class of cell adhesion receptors." (PMID 35300411, 2022). "For instance, the interaction of the V2 functional site at the von Willebrand factor type C repeat (vWC) domain of CCN1 with integrin αvβ3 in endothelial and cancer cells is critical for angiogenic and proliferative activities in embryonic development and tumor growth." (PMID 35148282, 2022). "In addition, it has been reported that CCN1 can facilitate macrophage migration and infiltration in tumor tissues." (PMID 35785168, 2022). "We note with interest that current tumor transcriptional databases cannot distinguish whether CCN1 expression changes are due to CCN1 expressed by the tumor, muscle, or endothelium." (PMID 35300411, 2022). "In a similar manner, the contractile smooth muscle microenvironment may induce CCN1 secretion as a de-differentiation factor in the muscle and function as a paracrine factor to clear a path for tumor invasion into and through the smooth muscle environment." (PMID 35300411, 2022). "To more strictly assess the effect of CCN1 on macrophage migration and tumor growth, we conducted conditional small hairpin RNA (shRNA)-mediated knockdown of CCN1 using lentiviral vectors in DGCs from patient-derived GBM cells (MGG4 and MGG8 DGCs) and U87ΔEGFR cells." (PMID 33618763, 2021). "Additionally, in vitro and in vivo xenograft model experiments provided further support for the aggressive nature of the tumours with CCN1 overexpression." (PMID 34205668, 2021). "Moreover, the results suggest a correlation between tumour grade and CCN1 concentration in tissue and blood of patients." (PMID 35052688, 2021). "CCN1 can increase tumor invasion and metastasis through various mediators." (PMID 34940056, 2021). "In addition, samples from patients with recurrent tumours showed a significant increase in CCN1 levels both in tumour tissues as well as in blood samples in comparison to the primary tumour and blood sample." (PMID 35052688, 2021). "Thus, CCN1 expression of leukemic cells seems to enhance tumor cell growth as well as drug resistance in both CML and ALL." (PMID 33428075, 2021). "The tumor inhibitory function of CCN1 has been revealed in quite recent times." (PMID 34940056, 2021). "DGCs augment macrophage infiltration through CCN1 to promote tumor progression of GBM." (PMID 33618763, 2021). "Here, using DGC-specific transcriptomic signatures, we investigated the biological roles of DGCs in the tumor microenvironment, and demonstrate that DGCs accelerate GSCs-dependent tumor progression by shaping a mesenchymal microenvironment via CCN1-mediated macrophage infiltration." (PMID 33618763, 2021).
tumor (continued). "Furthermore, we present evidence that CCN1 plays a critical role in the progression of GBM with increased expression in higher-grade tumours and matched blood samples." (PMID 35052688, 2021). "Surprisingly, induced expression of Ccn1 in ECs induced active angiogenic vessels, representing a significant decrease in pericyte coverage, both in the central and peripheral regions of the tumour." (PMID 31429823, 2019). "CCN1 (CYR61) stimulates active angiogenesis in various tumours, although the mechanism is largely unknown." (PMID 31429823, 2019). "However, the expression levels of both Ccn1 and N‐cadherin were rather low in the lungs of non‐tumor‐bearing mice." (PMID 28694244, 2017). "Given this requirement for homophilic N‐cadherin interactions in heterotypic cell interactions, we tested the generality of whether CCN1 also controlled N‐cadherin expression in tumor cells and fibroblasts." (PMID 28694244, 2017). "First, we deciphered the mechanism by which CCN1 may affect endothelial cells and that could be relevant in a tumor context." (PMID 28694244, 2017). "In contrast to this, Johnson reported that recombinant CCN1 decreased the growth of a MM cell line at high concentrations and overexpression of CCN1 in MM cells reduced tumour growth, inhibited osteoclastogenesis and stimulated osteoblastogenesis in a mouse model of MM." (PMID 27485291, 2016). "Furthermore, we found that integrin α11 was highly expressed in ESCC tumor tissue and functional blocking integrin α11 diminished CCN1-induced β-catenin elevation and translocation." (PMID 22701179, 2012). "Conversely, loss of Ccn1 expression did not appreciably affect tumor growth." (PMID 38363129, 2024). "Indeed, flow cytometry with anti-CD4 antibodies revealed that, whereas few T cells penetrated the tumors embedded within a wild-type tumor stroma, there was a trend toward more CD4+ T cells (P = 0.057) being observable in CCN1-deficient stroma (1.20% ± 0.45% vs. 12.07% ± 4.06%, CCN1f/f vs. CCN1−/−)." (PMID 38363129, 2024). "Thus, the model used is suitable for this study as we are interested in examining the interplay of Col1A2-Cre-fibroblasts with the tumor environment and, specifically, the role of the matricellular protein CCN1 in coordinating this process, including its potential role in ICI resistance." (PMID 38363129, 2024). "However, CCN1 overexpression weakened the inhibitory effect of VB on tumour growth." (PMID 35785168, 2022). "High expression of CCN1 was associated with shorter overall survival (OS) in five types of cancer [ACC, BLCA, brain lower grade glioma (LGG), mesothelioma (MESO), and stomach adenocarcinoma (STAD)] and longer OS only in SKCM, suggesting its role as a tumor suppressor." (PMID 33833779, 2021). "Thus, in AML, CCN1 seems to have a pro-leukemic effect in both tumor and stromal cells." (PMID 33428075, 2021). "Besides the proliferation, previous studies suggested that CCN1 may be involved in tumor cell migration and invasion." (PMID 33105556, 2020). "A group of researchers has shown that the CCN1 may serve as a tumor suppressor in NSCLC." (PMID 33105556, 2020). "We propose that clinical targeting of CCN1 may be beneficial in reducing tumor growth, invasion, and angiogenesis, and we demonstrate that targeting CCN1 in the vasculature, which is easily accessible to therapeutics, could also prevent cancer intravasation and subsequent metastasis." (PMID 28694244, 2017). "Finally, atomic force microscopy analysis of the tissues determined that peri‐necrotic tumor areas (bona fide highly expressing Ccn1) were much stiffer than the non‐necrotic areas and that stiffness was within a range comparable to those recapitulated in vitro with the PAGs." (PMID 28694244, 2017). "CCN1 is released from or produced by activated platelets at levels more than 20-fold higher than any other growth factors, suggesting that platelets constitute a novel source of CCN1 release and may play central roles in tumor progression." (PMID 26497214, 2016).
tumor (continued). "Because pharmacological and genetic ablation of FASN overcomes tumor regrowth and metastasis after antiangiogenic therapy withdrawal, it might be worthwhile to evaluate whether the CCN1 Æ FASN angiogenesis/lipogenesis axis is responsible for the resistance to antiangiogenic therapies." (PMID 27713913, 2016). "Interestingly, the effects of recombinant CCN2 peptide on U-CH1 cells were more pronounced under normoxia than hypoxia, promoting increased expression of CCN1, CCN2, CCN3 and CCN5, the notochord-associated markers SOX5, SOX6, T, CD24, and FOXA1 as well as increased tumour-sphere formation." (PMID 25541962, 2014). "Through these diversity of functions, CCN1 modulates important biological processes including developmental processes, angiogenesis and tissue regeneration, and plays a role in pathological conditions such as wound healing, vascular diseases, inflammation, fibrosis and tumor development." (PMID 24965524, 2014). "We evaluated the cell proliferation of Ccn1 by subcutaneously injecting Ccn1 knockout KPC and Pan02 cells into nude mice and monitored the tumor volumes every two days until the mice were sacrificed for 25 days post‐implantation." (PMID 40287974, 2025). "In this paper, we focused on CYR61, also known as CCN1, which has been shown to act as a tumor-promoting factor and is likely a key regulator of cancer progression." (PMID 41009559, 2025). "Mechanistically, VB directly binds and downregulates CCN1, an oncogenic factor highly expressed in OC, inhibiting the AKT/NF-κB pathway, which plays a central role in regulating tumor progression and macrophage polarization." (PMID 40330466, 2025). "It is demonstrated that Ccn1 promotes PDAC progression by upregulating collagen and chemokine expression, thereby facilitating immune cell exclusion and enhancing tumor growth." (PMID 40287974, 2025). "As a member of the CCN family of matricellular proteins, CCN1 is known to regulate cell–ECM interactions and promote tumor cell migration, intratumoral angiogenesis, and ECM remodeling through collagen production and deposition." (PMID 40416783, 2025). "Analysis of publicly available datasets demonstrated an upregulation of CCN1 and CCN2 expression in tumor tissues and normal adjacent mucosa compared to healthy colon mucosa tissues." (PMID 38981023, 2024). "BATF2 blocks tumor progression through multiple mechanisms, such as the inhibition of epithelial–mesenchymal transition (EMT), CCN1 transcription, c-Jun expression, and angiogenesis." (PMID 39678510, 2024). "NF-κB plays an important role in CAFs, mediating the upregulation of proteases such as COX2, CXCL1, CXCL2, CYR61/CCN1, IL-1β, IL-6, and osteopontin, thus promote tumor growth, recruit macrophages, and form tumor vasculature." (PMID 39146202, 2024). "Similar to CCN1, S100A8 was firstly reported to take part in reconstruct tumor microenvironment by recruitment of immune cells, leading to tumor growth, metastasis, and premetastatic niche formation." (PMID 39659236, 2024). "To further support the correlation between CCN1 and its related genes, we analyzed the publicly available microarray dataset GSE71729 of PDAC tumor samples." (PMID 39273316, 2024). "Considering the anti‐tumor effects of CCN1 silencing in the MES‐GSCs, we overexpressed CCN1 in the PN‐GSC 8–11 to further confirm its pathophysiological role." (PMID 39659236, 2024). "Increased expression of CCN1, CCN2, CCN3 and CCN4 is closely related with cell adhesion, proliferation and migration, and thus they can contribute directly to tumorigenesis, tumor development and metastases." (PMID 34940056, 2021). "We also present clear evidence that CCN1 has a pivotal role in the progression of GBM, as we present evidence that its increased expression in higher grade tumours is correlated with higher concentrations in patient blood." (PMID 35052688, 2021).
tumor (continued). "CCN1 and CCN3 have been shown to exhibit a dual nature of tumor inhibition and tumor suppression to some extent in quiet recent time." (PMID 34940056, 2021). "Among them, cysteine-rich 61 (CYR61, also named CCN1) attracted our attention because it was located in tumor angiogenesis signaling pathway gene sets and was significantly downregulated by MIIP overexpression." (PMID 34931765, 2021). "CCN1, a transcriptional target of YAP/TAZ/TEAD, is secreted from various cell type, including, tumor cells, endothelial cells, fibroblasts, and smooth muscle cells." (PMID 33618763, 2021). "In colon cancer, the increased CCN1, CCN2, and CCN4 were considered as an indicator for the tumor stages." (PMID 33105556, 2020). "CCN1 is a well-known transcriptional target of YAP/TAZ, is secreted in cancer cells, and induces extensive tumour angiogenesis, underscoring its paracrine angiogenic effect." (PMID 31429823, 2019). "Secreted CCN1 is reported to facilitate EC migration and tumour angiogenesis via a paracrine effect, and YAP, an upstream regulator of CCN1, is expressed in the developing front of mouse retinal vessels." (PMID 31429823, 2019). "CCN1/CYR61 is also noted as a famous downstream target of YAP1 in cancers, contributing to tumor growth." (PMID 30934860, 2019). "Using a xenograft model we demonstrated that cyr61/CCN1 silencing in Panc-1-SP cells reverses the stemness features and tumor initiating potency of these cells." (PMID 21232118, 2011). "For example, molecular evidence has demonstrated that CCN1 and CCN2 contribute to glioma tumour progression." (PMID 18789696, 2008). "CCN1 and CCN2 expression levels also correlate positively with tumour grade and pathology and are prognostic indicators of patient survival in these tumours." (PMID 18789696, 2008). "Additionally, Ccn1‐KO tumors demonstrated significantly higher protein levels of TNFα, IL2, and IFNγ in tumor and serum." (PMID 40287974, 2025). "Additionally, endothelial expression of cellular communication network factor 1 (CCN1) promotes stable adhesion of tumor cells to blood vessels, while ephrin-B2 expression drives the perivascular invasion of tumor stem cells." (PMID 40995371, 2025). "The CCN protein family, particularly cysteine-rich protein 61 (CYR61/CCN1) and connective tissue growth factor (CTGF/CCN2), have been identified as downstream transcriptional targets of YAP and are markedly upregulated in keratinocytes within BCC tumor nests." (PMID 41550920, 2025). "Note that in both experimental groups few T cells were detected in the tumor is consistent with the notion that B16F10 tumors are poorly immunogenic, and that loss of CCN1 expression in fibroblasts does not result in decreased tumor size (this article)." (PMID 38363129, 2024). "These resultswarrant the need for investigating the mechanism of action of PROSER2.For instance, proteins such as CCN1, the expression of which was decreasedin PROSER2-expressing cells, may be involved in promoting cell migrationand tumor vascularization." (PMID 38293943, 2024). "Following administration, OVs modulate the tumor microenvironment by attracting bone marrow-derived macrophages and brain resident microglia to the OV-injected tumor site through the release of chemoattractants by OV-infected tumor cells, such as CCL2 and CCN1." (PMID 37234776, 2023). "Members of CCN family, including CCN1‐6, are evolutionarily conserved and participate in regulating different pathophysiological processes, including cell proliferation, adhesion, angiogenesis, ECM modeling, migration, tumor growth (Jun and Lau, 2011)." (PMID 38268722, 2023). "Furthermore, a strong staining for Ccn1 was measured in blood vessels of the B16F10 tumors, which highlights the relevance of this tumor model for our study." (PMID 28694244, 2017). "In addition, the other CCN family members including CCN1, CCN2, and CCN3 also were higher in tumor than in normal." (PMID 26824419, 2016).
tumor (continued). "In addition, this study did not assess CCN1 expression in the GBM tumor microenvironment in the context of other key cell types (e.g. astrocytes, neurons, and microglia)." (PMID 39659236, 2024). "Besides, CYR61 (cysteine-rich angiogenic inducer 61, CCN1), another oncogene stimulating Wnt/β-catenin pathway, has been reported to be targeted and downregulated by miR-142-5p, an anti-tumor miRNA." (PMID 37386429, 2023). "However, based on GBM data from the TCGA, CCN1 levels showed equivalent transcription levels between GBM tumor and non-neoplastic brain tissue samples." (PMID 35910786, 2022). "Collectively, from these experiments, we assumed that the activation of Cyr61/CCN1 may play a critical role in the reprogramming and maintenance of cancer stemness/tumor initiating cells through EMT process in parental counterparts, and subsequently enhance the migration of these cells." (PMID 21232118, 2011). "To begin to determine what might be the role of CCN1 expression by CAFs, we used CAF single-cell expression data to identify a group of six genes (PDGFRA, COL1A1, DCN, TAGLN, COL6A3, and LPAR1) that strongly correlated with CCN1 expression, yet were minimally expressed in other tumor cell types." (PMID 38363129, 2024). "In addition, induction of CCN1/Cyr61 and CCN5/WISP2 was also found in the CCA tumors, whereas CCN3/NOV and CCN6/WISP3 did not have obvious changes in both the nontumor and tumor samples from the CCA tissues." (PMID 27829832, 2016).